HNRNPA1 (heterogeneous nuclear ribonucleoprotein A1)
Diseases named in the same sentence as HNRNPA1 in open-access papers (continued):
Sharing a sentence is not in itself a finding about the gene and the disease.
pancreatic cancer (9 papers, 2013 to 2025). "Recent studies have shown that hnRNPA1 enhances tubule formation and migration of lymphoendothelial cells through extracellular vesicle transport, thereby promoting metastasis of pancreatic cancer." (PMID 38810697, 2024). "Quercetin decreased hnRNPA1 protein levels in a dose- and a time-dependent manner in both thyroid and pancreatic cancer cells." (PMID 31480735, 2019). "Thyroid and pancreatic cancer cells were transfected with hnRNPA1 siRNA and co-treated with BET inhibitors." (PMID 31480735, 2019). "In pancreatic cancer, PRMT3 enhances chemoresistance by methylating heterogeneous nuclear ribonucleoprotein A1 (hnRNPA1), which stabilizes ABCG2 mRNA." (PMID 40050608, 2025). "In our recent study, we discovered that the protein hnRNPA1, shuttled by EVs originating from KRASG12D pancreatic cancer cells, serves to promote lymphangiogenesis and lymph node (LN) metastasis." (PMID 38012734, 2023). "Overall, we demonstrate that targeting of hnRNPA1 by Quercetin enhances the efficacy of BET inhibitors in thyroid and pancreatic tumors." (PMID 31480735, 2019). "Given co-expression of hnRNPA1 and the BET protein BRD4 in human thyroid and pancreatic tumors, and the favorable safety profiles of Quercetin and BET inhibitors, our study provides a rationale for pursuing this combination therapy in advanced cancer patients." (PMID 31480735, 2019). "While the role of hnRNPA1 in thyroid cancer progression has not been described, hnRNPA1 has previously been shown to regulate oncogenic Kras signaling in pancreatic cancer cells to mediate pancreatic cancer progression." (PMID 31480735, 2019). "Here we show that hnRNPA1 knockdown, similar to Quercetin treatment, can enhance the effects of BET inhibitors on proliferation, apoptosis, and cell survival in both thyroid and pancreatic cancer cells." (PMID 31480735, 2019). "Importantly, Quercetin did not affect hnRNPA1 mRNA levels in thyroid and pancreatic cancer cells." (PMID 31480735, 2019).
spinal muscular atrophy (9 papers, 2014 to 2025). A motor neuron disease that affect the muscles, and characterized by muscle weakness and atrophy resulting from progressive degeneration and irreversible loss of the anterior horn cells in the spinal cord (i.e., lower motor neurons) and the brain stem nuclei. "For example, a silent variation in SMN2 was hypothesized to create a binding site of the repressor hnRNPA1 which reduced the inclusion of exon 7 of SMN2 and caused spinal muscular atrophy." (PMID 25985083, 2015). "To screen for additional hnRNPA1 mutations in patients, we surveyed a large cohort of 547 patients with distal HMN (dHMN), axonal Charcot-Marie-Tooth disease (CMT2), intermediate CMT (CMTi), spinal muscular atrophy (SMA), ALS, hereditary spastic paraplegia (HSP), and myopathy." (PMID 34291734, 2021). "For example, the SSO Nusinersen that treats Spinal Muscular Atrophy targets the intron downstream of exon 7 in the SMN2 pre-mRNA, to block binding of the splicing repressor hnRNPA1." (PMID 38664594, 2024).
Alzheimer disease (8 papers, 2014 to 2024). A progressive, neurodegenerative disease characterized by loss of function and death of nerve cells in several areas of the brain leading to loss of cognitive function such as memory and language. "Of note, reduced levels of hnRNPA1 and hnRNPA2B1 have been reported in cases of Alzheimer’s disease, suggesting a connection between RBP homeostasis and neuronal health in multiple disorders." (PMID 30937520, 2019).
glioma (8 papers, 2014 to 2022). A benign or malignant brain and spinal cord tumor that arises from glial cells (astrocytes, oligodendrocytes, ependymal cells). "Cancer transcription factor MYC up-regulates the mRNA expression of hnRNPA1 and hnRNPA2 in gliomas, which promotes the synthesis of pyruvate kinase M subtype 2 (PKM2) and participates in glycolytic transformation." (PMID 33488680, 2020). "The effects of c-Myc in increasing PKM2 expression are mediated through its up-regulation of hnRNPA1 in glioma cells." (PMID 25948776, 2015). "These date indicate that hnRNPA1 inhibits let-7a expression in glioma cells, and that the inhibition occurs at the level of biogenesis." (PMID 25948776, 2015). "Previous studies have shown that hnRNPA1, as a protein-coding gene, is up-regulated in glioma." (PMID 36246611, 2022). "Moreover, the PTBP1 and hnRNPA1 expression in glioma and neuroblastoma is regulated by MYC, a protein which is often overexpressed in cancer and can impair alternative splicing." (PMID 36230624, 2022). "The down-regulation of c-Myc/hnRNPA1/PKM2 by let-7a is verified using a glioma xenograft model." (PMID 25948776, 2015). "We established a role for let-7a/c-Myc/hnRNPA1/PKM2 signaling in glioma cell glucose metabolism." (PMID 25948776, 2015). "Thus, the let-7a/c-Myc/hnRNPA1/PKM2 signaling pathway may serve as the potential target for glioma therapy." (PMID 25948776, 2015). "hnRNPA1, also known as ROA1, is up-regulated in a large number of cancers such as colorectal, breast, gliomas, and lung." (PMID 33053689, 2020). "We demonstrated that let-7a, c-Myc and hnRNPA1 form a feedback loop to modulate PKM2 expression, thereby influencing glioma cell glucose metabolism and growth." (PMID 25948776, 2015). "Our results suggest that let-7a, c-Myc and hnRNPA1 form a feedback loop to modulate PKM2 expression, therefore regulating glioma cell glucose metabolism." (PMID 25948776, 2015). "During splicing, three heterogeneous nuclear ribonucleoprotein (hnRNP) proteins-- hnRNPA1, hnRNPA2 and polypyrimidine tract binding protein (hnRNPI, PTB)--bind repressively to exon 9 to facilitate the exclusion of exon 9 and the generation of PKM2 in glioma." (PMID 25948776, 2015). "We also detected the expression of let-7a, c-Myc, hnRNPA1 and PKM2 in glioma tissues by qRT-PCR." (PMID 25948776, 2015).
viral infection (8 papers, 2015 to 2023). "During viral infection and cellular stress, activation of the innate immune response causes a redistribution of the cytoplasmic HNRNPA1 process." (PMID 36066672, 2022). "hnRNPA1 is a nuclear protein known to alter its subcellular location in response to viral infections, mitochondrial localization of this RBP in IAV infection is very interesting." (PMID 35215793, 2022). "There is mounting evidence that hnRNPA1, an RNA binding protein, interacts with many viral gene products and differentially regulates host-virus gene expression in viral infections." (PMID 35215793, 2022). "It is shown that in Sindbis virus, EV-71, human rhinovirus (HRV), porcine epidemic diarrhea virus (PEDV) infections, hnRNPA1 promotes viral infection." (PMID 35215793, 2022). "Cellular translocation of hnRNPA1 in response to external stimuli like stress, osmotic shock, or viral infections is well known; however, its expression and temporal distribution in IAV infection are rather elusive." (PMID 35215793, 2022). "As a host factor, hnRNPA1 responds to virus infection variously." (PMID 37005771, 2023). "In the context of viral infection, hnRNPA1 plays a major functional and regulatory role, and while it was found to enhance some viral infections, such as sindbis virus, enteroviruses, and rhinovirus, it counteracted Human T cell lymphotropic virus (HTLV-1) and hepatitis C virus (HCV) infections." (PMID 34835333, 2021). "Both hnRNPA1 and HSPA8 have an ambiguous influence on viral infection: they can enhance replication of some viruses, but they decrease it for some others." (PMID 33198321, 2020). "Of these, only a few parent genes code for proteins that are known to have a role in viral infection, such as HNRNPA3/HNRNPA1." (PMID 26426037, 2015).
lung adenocarcinoma (7 papers, 2019 to 2024). A carcinoma that arises from the lung and is characterized by the presence of malignant glandular epithelial cells. "LncRNA HOTAIR and HNRNPA1 are reported to play an oncogenic role in non-small cell lung cancer, and the overexpression of HNRNPA1 is shown to promote the proliferation of lung adenocarcinoma cells." (PMID 33102210, 2020). "A role of hnRNPA1 for cell cycle control is also confirmed in vitro, since knockdown of hnRNPA1 has been shown to inhibit proliferation of lung adenocarcinoma through arrest at the G0/G1 phase of the cell cycle." (PMID 32417965, 2020). "HNRNPA1 is reported to be overexpressed in lung adenocarcinoma tissues and may play an oncogenic role in lung adenocarcinoma." (PMID 33102210, 2020). "It is suggested that HNRNPA1 acted as an oncogene in lung adenocarcinoma." (PMID 33102210, 2020). "In lung adenocarcinoma, ESCO2, as an evolutionarily conserved cohesion acetyltransferase, can catalyze hnRNPA1 acetylated at K277 and retain hnRNPA1 in the nucleus." (PMID 38785973, 2024).
motor neuron disease (7 papers, 2014 to 2023). "Similarly, mutations in FUS, HNRNPA1/B2, and other RNA-binding proteins have been associated with familial forms of motor neuron disorders." (PMID 37730840, 2023). "MATR3-related pathology, encompassing myopathy and motor neuron disease, represents an illustrative example of multisystem proteinopathy (MSP), such as other diseases associated to mutations in VCP, HNRNPA2B1, HNRNPA1, and SQSTM1 genes." (PMID 34659085, 2021). "SG component proteins with a causal role for motor neuron diseases include TDP-43 (gene symbol TARDBP), FUS, ATXN2, SMN, Tau (gene symbol MAPT), HNRNPA2B1, and HNRNPA1." (PMID 24659297, 2014). "Based on these findings, we suggest that it could be beneficial to test patients with a range of motor neuron diseases, including dHMN, atypical and typical ALS, as well as (distal) myopathy and MSP phenotypes, for pathogenic HNRNPA1 variants." (PMID 34291734, 2021). "Mutations in FUS, hnRNPA1/B2 and other RBPs are associated with familial forms of motor neuron disorders, while mutations in proteins associated with formation or removal of RNA granules cause ALS, FTLD, other motor neuron diseases as well as myopathies." (PMID 28420962, 2017). "Finally, FUS pull down led to the identification of several interactors with known roles in motor neuron disease or other neurodegenerative disorders, including hnRNPA1, hnRNPA2B1, Matrin3 and FMRP." (PMID 27164932, 2016). "Furthermore, the protein products for several genes that have been causally linked to ALS are found within the M2 module, including HNRNPA1, MATR3, and PFN1 and TDP‐43 itself, whereas HSPB1 (in M6) has been linked to hereditary motor neuropathy, a form of motor neuron disease." (PMID 29191947, 2018).
neuroblastoma (7 papers, 2015 to 2025). Neuroblastoma (NB) is the most common solid, extracranial childhood tumor. "Notable DSGs included PKM, which has already been shown to undergo hnRNPA1-dependent alternative splicing in neuroblastoma and MLX, encoding a MYCN transcriptional co-activator regulating glutamine metabolism genes in neuroblastoma." (PMID 39313128, 2024). "Protein level changes of hnRNPA1 following GSK3203591 treatment were also confirmed in MNA neuroblastoma cell-lines." (PMID 39313128, 2024). "We report in human brain and human SH-SY5Y neuroblastoma cell lines that DJ-1 predominantly forms high molecular weight (HMW) complexes that included RNA metabolism proteins hnRNPA1 and PABP1 and the glycolysis enzyme GAPDH." (PMID 29016861, 2017). "Interestingly, hnRNPA1 was previously demonstrated to be a MYCN target gene mediating AS in neuroblastoma, and a comparison of our DSGs with DSGs reported in RNAseq of hnRNPA1/PTBP1 knockdowns demonstrated a significant overlap." (PMID 39313128, 2024). "Additionally, a recent study in neuroblastoma cells found multiple nuclear protein partners for TIMAP, including splicing factor proline- and glutamine-rich (SFPQ) proteins and heterogeneous nuclear ribonucleoprotein A1 (hnRNPA1)." (PMID 41170526, 2025).
cervical cancer (6 papers, 2020 to 2024). A primary or metastatic malignant neoplasm involving the cervix. "In the present work, we have demonstrated the function of HNRNPA1 in HPV-associated cervical cancer." (PMID 33457194, 2020). "Here, we show the increased expression level of heterogeneous nuclear ribonucleoprotein A1 (HNRNPA1) in HPV-associated cervical cancer cells including HeLa, Caski, and SiHa cells, especially in HeLa cells." (PMID 33457194, 2020). "Studies have shown that ubiquitin-specific protease 7 could promote cervical carcinogenesis, while HNRNPA1 was a good diagnostic marker for cervical cancer." (PMID 32793282, 2020). "Thus, the function of HNRNPA1 in HPV-associated cervical carcinoma warranted further investigation." (PMID 33457194, 2020). "For molecular screening, we selected GAPDH as the biomarker for cervical precursor lesions and HNRNPA1 as the biomarker for cervical cancer -chosen from the three previously identified options based on antibody availability- to be detected in sera." (PMID 39610929, 2024). "For instance, hnRNPA1 is highly expressed in cervical cancer cells and can disrupt cancer-related genes." (PMID 33498485, 2021). "As a crucial component in alternative splicing, scrutinising the aberrant splicing induced by hnRNPA1 in cervical cancer is critical." (PMID 33498485, 2021). "Another recent study investigated prognostic biomarkers of alternative splicing in cervical cancer and revealed hnRNPA1, ubiquitin C, and RNA polymerase II subunit L as effective prognostic biomarkers." (PMID 33498485, 2021). "And inhibition of HNRNPA1 attenuated the proliferation, invasion, and migration of HeLa cells, which indicated that HNRNPA1 represented a potential target for HPV-associated cervical carcinoma." (PMID 33457194, 2020). "Moreover, hnRNPA1 was found to be highly expressed in other cancer types, including cervical cancer, where it plays a crucial role in cancer cell growth, survival, and metabolic alterations, positioning it as an active driver of cancer progression." (PMID 39834948, 2024). "hnRNPA1 is thus a good biomarker for cervical cancer diagnosis." (PMID 33498485, 2021).
liver cancer (6 papers, 2020 to 2025). An epithelial or non-epithelial malignant neoplasm that arises from the liver. "This interaction further influences tumor metastasis, providing fresh insights and a theoretical framework for understanding the role of hnRNPA1 in the advancement of liver cancer." (PMID 39834948, 2024). "In this investigation, we observed a pronounced elevation of hnRNPA1 expression in liver cancer tissues using the TCGA public database." (PMID 39834948, 2024). "BC15 is an HNRNPA1-specific single-stranded DNA aptamer whose inhibitory effect on liver cancer cell proliferation is even stronger than that of HNRNPA1 small interfering RNA, suggesting its potential as a candidate inhibitor of HNRNPA1." (PMID 39062595, 2024). "Then software analysis enabled us to determine that the AS patterns of ZNF207 are altered in liver cancer tissues when hnRNPA1 expression is reduced." (PMID 39834948, 2024). "Moreover, according to the HPA database, hnRNPA1 is indicated as a prognostic marker in liver cancer (p < 0.001), which underscores its relevance in HCC." (PMID 40340965, 2025). "Moreover, the interaction of DANCR with heterogeneous nuclear ribonucleoprotein A1 (HNRNPA1) in HepG2 and Huh7 cells enhances HNRNPA1 expression by preventing its degradation and facilitating the EMT, invasion, and migration of liver cancer cells." (PMID 38877534, 2024).
sarcoma (6 papers, 2018 to 2025). A usually aggressive malignant neoplasm of the soft tissue or bone. "Among the genes mutated in ALS, however, several—including those for TDP-43 (TAR DNA-binding protein–43), MATR3 (matrin 3), FUS (fused in sarcoma), and hnRNPA1 (heterogeneous nuclear ribonucleoprotein A1)—encode RNA-binding proteins (RBPs) that share an important role in RNA metabolism." (PMID 40707625, 2025). "Some ALS-causing gene mutations encode RBPs, including transactive response DNA-binding protein 43 (TARDBP, which encodes TDP-43), fused in sarcoma/translocated in liposarcoma (FUS/TLS or FUS) and heterogeneous nuclear ribonucleoprotein A1 (hnRNPA1)." (PMID 34396115, 2021). "Human regulatory proteins HNRNPA1 (heterogeneous nuclear ribonucleoprotein A1), HNRNPC, HNRNPL, HuR (human antigen R), and protein LIN28A (lin-28 homolog A) were predicted to bind ebv-sisRNA-1 and/or ebv-sisRNA-2; FUS (fused in sarcoma) was predicted to associate with ebv-sisRNA-2." (PMID 29458410, 2018). "These proteins are fused in sarcoma (FUS), heterogeneous nuclear ribonucleoprotein A1 (hnRNPA1), and the TAR DNA-binding protein 43 (TDP-43)." (PMID 34762868, 2021). "Many ALS-causing gene mutations encode RBPs, including transactive response DNA-binding protein 43 (TDP-43), fused in sarcoma/translocated in liposarcoma (FUS/TLS or FUS) and heterogeneous nuclear ribonucleoprotein A1 (hnRNPA1)." (PMID 33172210, 2020).
head and neck cancer (5 papers, 2021 to 2023). A primary or metastatic malignant neoplasm affecting the head and neck. "For example, a recent study demonstrated that hnRNPA1 regulates the packaging of miR-196a into cancer-associated fibroblast-derived exosomes by binding to its UAGGUA motif and plays an active role in head and neck cancer progression and chemoresistance." (PMID 35410432, 2022). "And Exosome packaging microRNAs requires the involvement of regulatory factors, hnRNPA1 accelerated exosomal miR-196a packaging in head and neck cancer." (PMID 33999859, 2021).
liver fibrosis (5 papers, 2020 to 2024). "ER stress in HSCs induces hepatic fibrosis by dysregulating miR-18, which is regulated by the activation of PERK and the destabilization of heterogeneous nuclear ribonucleoprotein A1 (HNRNPA1)." (PMID 39063116, 2024).
multiple myeloma (5 papers, 2017 to 2022). "NEK2 regulates the alternative splicing of PKM immature RNA in multiple myeloma cells by interacting with hnRNPA1/2." (PMID 28086949, 2017). "Similar to hnRNPA1/2, the expression of NEK2 was regulated by c-Myc at transcription level in myeloma cells." (PMID 28086949, 2017). "In this study, we have shown that NEK2 binds and interacts with hnRNPA1 and hnRNPA2, which control pyruvate kinase mRNA splicing in cancer cells, and increases PKM2 expression and PKM2/PKM1 ratio in myeloma cells." (PMID 28086949, 2017). "HNRNPA1/2 proteins may interact with NEK2 to regulate PKM splicing and promote aerobic glycolysis in multiple myeloma." (PMID 35897085, 2022).
bladder cancer (4 papers, 2022 to 2025). "By inhibiting hnRNPA1-dependent PKM splicing and consequent PKM2 overexpression, RBMX neutralizes the aggressive phenotype of metastatic bladder cancer cells." (PMID 38785973, 2024). "With low expression in metastatic bladder cancer tissues, RBMX can competitively bind to the RGG motif of hnRNPA1 and block it from combining with the lateral intron of PKM mRNA exon 9, leading to high expression of PKM1 and weakening the malignancy and progression of tumors." (PMID 38785973, 2024).